INS (insulin)
Diseases named in the same sentence as INS in open-access papers (continued):
Sharing a sentence is not in itself a finding about the gene and the disease.
type 2 diabetes (continued). "Similarly, we found that C-peptide is associated with development of type 2 diabetes independent of insulin and other metabolic factors in a large population study." (PMID 32957570, 2020). "The schistosome-derived carbohydrate LNFPIII might be useful in treating type 2 diabetes as its administration in mice has improved glucose tolerance and insulin sensitivity, and in psoriasis as it induces Th2 immune response, and subsequent amelioration of skin lesions." (PMID 32582161, 2020). "However, their ability to induce insulin release from human islets at sub-stimulatory glucose concentrations contra-indicates against their use for treating type 2 diabetes as this could lead to hypoglycaemia in vivo." (PMID 31925452, 2020). "While higher circulating concentrations of both C15:0 and C17:0 have been associated with lower risks of type 2 diabetes, a controlled study in an animal model demonstrated that plasma increases of C17:0, and not C15:0, had linear correlations with decreased insulin and glucose." (PMID 32424181, 2020). "Moreover, (2s,3r,4s)-4-hydroxyisoleucine (4-HIL) naturally occurs in Trigonella foenum-graecum (fenugreek) seeds, accelerates insulin secretion, and could be administered to treat type II diabetes." (PMID 32731373, 2020). "Additionally, GLP-1 may improve insulin sensitivity in patients with type 2 diabetes and animal models." (PMID 31968646, 2020). "Furthermore, a T1D-GRS has the potential power to predict when those with type 2 diabetes may require insulin administration." (PMID 32797243, 2020). "Insulin therapy is frequently required to achieve glycemic targets (A1c) in type 2 diabetes (T2D); however, clinicians and patients face barriers with the complexities of multiple daily injection regimens." (PMID 33202616, 2020). "Diabetes is a metabolic disease caused by inadequate insulin action, resulting in high blood glucose diabetes, especially noninsulin-dependent diabetes mellitus (type 2 diabetes) characterized by postprandial hyperglycemia is a global health affecting about 90% of the patients." (PMID 33489029, 2020). "Type 2 diabetes mellitus (T2DM) develops as a result of progressive disorder in both mechanisms, insulin secretion and insulin resistance." (PMID 32344535, 2020). "Artemisia dracunculus has been used for glycemic control, insulin sensitivity, and insulin secretion and likewise, A. princeps was evaluated for the same effects in subjects with impaired fasting glucose and mild-type 2 diabetes and A. absinthium in the control of diabetes type 2." (PMID 33396790, 2020). "Thus, microvascular endothelial dysfunction seems to be involved in the development of early derangements in glucose and insulin metabolism and may thereby trigger the development of prediabetes and type 2 diabetes." (PMID 32690629, 2020). "If pancreatic islet GABA concentration changes out of the physiological range or the pulsatile GABA release is disturbed, it may impair proper insulin and glucagon secretion, potentially alter cell fate and eventually contribute to pathogenesis of type 2 diabetes." (PMID 31963438, 2020). "The renin-angiotensin system (RAS) is critical in the regulation of glycolipid metabolism and insulin sensitivity, which are closely related to metabolic syndromes [e.g., obesity, type 2 diabetes mellitus (T2DM), and non-alcoholic fatty liver disease (NAFLD)]." (PMID 32322207, 2020). "In the second step of the MR analysis, conducted in WHI, we fitted a similar basic model for associations between cg06500161 methylation and type 2 diabetes in all participants, as well as cg06500161 and fasting glucose, cg06500161 and fasting insulin in the non-diabetic participants." (PMID 32612641, 2020).
type 2 diabetes (continued). "The primary aim of our study was to examine the association between C-peptide levels and risk of developing type 2 diabetes, independent of glucose and insulin levels, in a large population-based cohort study with younger age than has been previously evaluated for a long follow-up period." (PMID 32957570, 2020). "Moreover, it has been hypothesized that amino acids change significantly in the circadian misalignment individuals with of type 2 diabetes, prediabetes/obesity, reduced insulin sensitivity and impaired glucose homeostasis and those consuming a high-fat diet." (PMID 31992312, 2020). "Using the insulin group as the reference, the risks of adverse pregnancy outcome in the switching group and the metformin group were computed using generalized estimation equations, adjusting for patient age, duration of type 2 diabetes, hypertension, hyperlipidemia, retinopathy, and aspirin use." (PMID 32887578, 2020). "Importantly, exposure to inflammatory cytokines, such as TNF and IL-6, and activation of NF-κB in muscle can decrease oxidative metabolism, induce atrophy, and prevent insulin-stimulated Akt phosphorylation, all of which are factors in the development of type 2 diabetes and metabolic syndrome." (PMID 32591558, 2020). "Therefore, post-meal walking may be as effective as one prandial insulin in control of PPG in type 2 diabetic patients who fail from basal insulin at least in short-term basis." (PMID 32236116, 2020). "Regular and increasing physical activity improve glycaemic control and reduce peripheral resistance to insulin, which hitherto played a protective role in reducing the formation of advanced glycation end products, a precursor of musculoskeletal complications in patients with type 2 diabetes." (PMID 33883840, 2020). "However, epigenetic modifications of PDX1 reducing its activity could contribute to the development of type 2 diabetes since this transcription factor binds to the promoter of a large set of genes related to β-cell survival as well as insulin secretion." (PMID 31682591, 2020). "Although the roles of Serpina11, Cdh16, Lrrc27, and Lrrc66 in regulating islet function remain unclear, Acod1 is known to be important in modulating the immune system and mitochondrial function, and Fgf21 can protect against type 2 diabetes in mice by increasing insulin expression and secretion." (PMID 32527043, 2020). "Notably, the risk of hypoglycaemia could be higher with ‘training low’, especially in individuals with uncontrolled or insulin-treated type 2 diabetes." (PMID 32529411, 2020). "However, this dysfunction is of concern, since the high demand for insulin secretion in response to chronic resistance to this hormone results in the progressive impairment of pancreatic β-cells and consequently the development of type 2 diabetes." (PMID 32187264, 2020). "Type 2 diabetes mellitus (T2DM) accounts for 90% of the diabetic population and is correlated with obesity-induced insulin resistance accompanied by a high rate of insulin secretion from pancreatic β-cells." (PMID 34803265, 2020). "A high-starch diet is on average also higher in fiber, and fiber have been associated with lower risk of type 2 diabetes, which is supported by the negative association between starch intake (expressed in E%) and fasting insulin and HOMA-IR in the full study sample." (PMID 33490099, 2020). "Type 2 diabetes mellitus (T2DM) is a systemic disease that is indicated by increasing blood sugar levels and is secondary to defect either in insulin production or insulin resistance." (PMID 33425511, 2020). "Genetically-predicted higher fasting insulin levels (using 18 SNP variants) and post-challenge insulin levels (using 17 SNP variants), but not fasting glucose (using 36 SNP variants) or Type 2 diabetes (using 49 SNP variants), were associated with increased risk of EC." (PMID 32397158, 2020).
type 2 diabetes (continued). "Chitosan oligosaccharide was used as a supplementary drug for improving the glycemic control of sitagliptin in type 2 diabetes mellitus (T2DM) by reducing insulin resistance and proinflammatory cytokines, and increasing insulin sensitivity." (PMID 33339290, 2020). "In conclusion, we demonstrated that obesity starting in the young age had deep consequences on the maturation of the PINS with later functional consequences on nervous control of insulin secretion in adult mice, which could lead to the development of type 2 diabetes." (PMID 31922022, 2020). "Interestingly, a medium-PRS, but not a high-PRS, was negatively associated with type 2 diabetes since SNPs for the best model were selected from the insulin/IGF-signaling pathway." (PMID 33114701, 2020). "A gradual decrease in the sensitivity of skeletal muscle to insulin is considered a primary event in metabolic disease progression, such as of type 2 diabetes (T2D)." (PMID 32178449, 2020). "However, whether other type 2 diabetes medications have an acute or chronic impact on insulin BBB transport or binding remain to be determined." (PMID 32704569, 2020). "The development of type 2 diabetes (T2D) is initially characterized by increased Insulin secretion by the pancreatic β cell to meet and overcome the demands of peripheral Insulin resistance." (PMID 32433667, 2020). "This study will not assess directly assess insulin secretion, glucose absorption through the gastrointestional tract, cardiovascular disease risk markers or other pesticides, chemicals, or endocrine disruptors linked to type 2 diabetes (e.g. phthalates)." (PMID 32154432, 2020). "However, there are still open questions regarding the optimal way to adjust a prandial insulin dose to a meal and the possible benefits for people with type 1 and type 2 diabetes if particular parameters of the meal are taken into account while calculating the prandial insulin dose." (PMID 30871141, 2019). "Type 2 diabetes mellitus (T2DM) is characterized by hyperglycemia due to impaired insulin secretion, as a result of degradation of incretin hormones." (PMID 31635140, 2019). "In addition, a considerable number of patients were being treated with sulfonylureas and/or alpha glucosidase inhibitors, and one patient in each group was being treated with pioglitazone, an insulin-sensitizing drug that has been shown to reduce VFA in patients with type 2 diabetes." (PMID 31192262, 2019). "For example, towards type II diabetes, Sancho and Pastore suggested that anthocyanin may lower blood glucose by improving insulin resistance, protecting β cells, increasing secretion of insulin and reducing digestion of sugars in the small intestine due to significant antioxidant characteristics." (PMID 30867679, 2019). "Altogether, oral administration of LECS remarkably attenuates features of type 2 diabetes on glucose, hepatic inflammation, insulin resistance, endothelial function, and vascular oxidative stress, being as most of these effects are related to insulin-dependent and insulin-independent mechanisms." (PMID 31636807, 2019). "Given evidence for a thin-fat insulin-resistant phenotype already being present in SA infants at birth, it is also possible that ethnic differences in gestational metabolites are important in the developmental origins of differences in type 2 diabetes and cardiovascular diseases between SAs and WEs." (PMID 31540515, 2019). "Type 2 diabetes mellitus (T2DM) occurs when insulin production is defective or its action on the metabolism of body sugars is defective." (PMID 31330902, 2019).
type 2 diabetes (continued). "As the major insulin target tissue and the predominant site of post-prandial glucose disposal, insulin resistance in skeletal muscle (SkM) is a defining feature of type 2 diabetes (T2D)." (PMID 32038288, 2019). "Moreover, patients with type 1 diabetes were excluded, which may ensure the use of insulin as a proxy for type 2 diabetes." (PMID 31798898, 2019). "The aim was to examine the relationship between changes in insulin exposure and arterial stiffness in type 2 diabetes (T2D)." (PMID 31119456, 2019). "Type 2 diabetes mellitus (T2DM) is a complex metabolic disorder, characterized by elevated blood glucose and attenuated insulin action." (PMID 31375554, 2019). "However, in a type 2 diabetes liver, not only higher levels of glycogenolysis and gluconeogenesis are detected, but also elevation of cholesterol and triglyceride synthesis are observed, suggesting that these pathways still are insulin sensitive." (PMID 30642126, 2019). "Therefore, DCAs were implied that it can be a useful alternative substrate in parenteral nutrition, sparing glucose utilization and increasing glycogen stores in those clinical conditions like type 2 diabetes, where reduced insulin‐induced glucose uptake and oxidation are observed." (PMID 31293078, 2019). "Genes for profiling in adipocytes were selected from genetic association studies for body mass index (BMI), Waist-to-hip ratio adjusted for BMI (WHRadjBMI), fasting insulin (Fins) and type 2 diabetes (T2D)." (PMID 30940487, 2019). "For example, apps with physical activity and healthy nutrition functions may be sufficient for patients recently diagnosed with type 2 diabetes, whereas those being treated with medications and insulin may require blood glucose and medication management functions." (PMID 30303485, 2019). "Novel non-insulin antidiabetic agents, especially SGLT-2 inhibitors and GLP1-RAs, offer substantial benefits, including weight loss and alteration of the underlying pathophysiology of type 2 diabetes, but also require screening and monitoring for adverse drug events." (PMID 31412090, 2019). "Type 2 diabetes mellitus (T2DM) is an extended metabolic disease recognized by hyperglycemia and, triggered by insulin resistance and diminished insulin release." (PMID 31275881, 2019). "Due to the ability of esculeoside A to improve the impaired glucose tolerance in treated db/db mice, we speculated that it is partly accountable for the treatment type 2 diabetes by improving the sensitivity of muscles or fat to insulin, thereby increasing their glucose uptake." (PMID 31215434, 2019). "We investigated the influence of resistance exercise (RE) with different intensities on HbA1c, insulin and blood glucose levels in patients with type 2 diabetes (T2D)." (PMID 30621076, 2019). "The aim of the study was to assess the prevalence of type 2 diabetes and other types of impaired glucose metabolism in bipolar patients along with an evaluation of the Fasting Triglycerides and Glucose Index (TyG) as a method of the insulin sensitivity assessment." (PMID 30934836, 2019). "Intensive insulin therapy providing strict glycemic control improved the median nerve conduction velocity, postural hypotension, and CV of the R-R intervals in patients with type 2 diabetes, whereas conventionally treated patients showed significant deterioration in autonomic function." (PMID 30857534, 2019). "Compromised function of insulin-secreting pancreatic β cells is central to the development and progression of Type 2 Diabetes (T2D)." (PMID 31346174, 2019). "Type 2 diabetes mellitus (T2DM) is a chronic metabolic disorder with decreased insulin action and hyperglycemia." (PMID 31208420, 2019). "However, insulin sensitivity data, which have been stratified for obese and non-obese in type 2 diabetes, have also shown no ethnic differences suggesting that our result is real and driven more by the presence of type 2 diabetes." (PMID 30729259, 2019).
type 2 diabetes (continued). "Diminished postprandial secretion of incretins and insulin represents one of the key pathophysiological mechanisms behind type 2 diabetes (T2D)." (PMID 30813546, 2019). "Additionally, we do not discard the possibility that MpHE through the activation of PPARγ, prevents IKK activity and therefore IRS phosphorylation on serine residues, thus improving insulin signaling directly on hippocampal neurons reversing the memory deficits observed in type II diabetes and AD." (PMID 31291963, 2019). "Regarding the role of IRS1 in the pathway of insulin signaling and the negative effect of rs10498210 polymorphism on the performance of this protein, it can be expected that this polymorphism is present in the etiology of type 2 diabetes." (PMID 30884193, 2019). "Type 2 diabetes (T2DM) is characterized by a combination of peripheral insulin resistance and inadequate pancreatic β-cell insulin secretion." (PMID 30761839, 2019). "Preclinical research has shown that insulin has a role in the central nervous system, where it regulates satiety signals and suppresses appetite, and it is suggested that these functions may be impaired in type 2 diabetes." (PMID 31576267, 2019). "However, the association between insulin therapy and this pro-arrhythmic status may be biased by the longer duration of type 2 diabetes usually seen in patients treated with insulin." (PMID 31540142, 2019). "The present study demonstrated an improvement in glycemic variability with the administration of fast-acting insulin aspart as compared to RHI, suggesting that modern bolus insulin replacement might prove to be a useful therapeutic strategy in type 2 diabetes patients with advanced CKD." (PMID 31886089, 2019). "Therefore, targeting insulin in the brain could be a valid approach for treating obesity and type 2 diabetes, provided that its functions in the brain remain intact." (PMID 30875909, 2019). "Implemented insulin mixture therapy was proved to be an important factor modifying the plasma profile of omentin-1, increasing the concentration of this bioactive protective molecule in the plasma of patients with type 2 diabetes, after 6 months of its use, in relation to pre-treatment situation." (PMID 31195747, 2019). "Type 2 diabetes mellitus (T2DM) is currently the most prevalent metabolic disease in the world and is characterized by insulin resistance, with an initial increase in insulin secretion, but subsequent beta cell death and insulin insufficiency over time." (PMID 30837966, 2019). "Additionally, independent predictors of change in FMD were age, duration of type 2 diabetes, treatment with basal insulin analogs, and treatment with DDP-4 inhibitors and GLP-1 receptor agonists (incretin-based agents), but not the change in HbA1c (p > 0.05) after 1 year of treatment." (PMID 31284526, 2019). "Chiglitazar, a dual PPAR-α/γ agonist, is an effective insulin sensitivity agent used to treat the major metabolic disorders of type 2 diabetes and may bring better impacts on lipid homeostasis through different mechanisms than selective PPAR-γ agonists in diabetic patients." (PMID 31699147, 2019). "Whereas, type 2 diabetes, formerly known as NIDDM was a metabolic disorder, which occurs due to the failure of insulin action." (PMID 31514311, 2019). "However, this method fails to detect BAT under insulin-resistant conditions associated with ageing and weight gain, such as type 2 diabetes." (PMID 30804455, 2019). "Little is known regarding initiation of insulin therapy in type 2 diabetes (T2D) in Central and South-Eastern European countries." (PMID 30993528, 2019). "In rodent models of type II diabetes, capsaicin application promoted chronic release of calcitonin gene-related peptide that led to impaired insulin secretion, while capsaicin-induced desensitization has been shown to improve insulin secretion in response to food intake." (PMID 31263706, 2019).